UBASH3B (ubiquitin associated and SH3 domain containing B)
Diseases named in the same sentence as UBASH3B in open-access papers (continued):
Sharing a sentence is not in itself a finding about the gene and the disease.
metabolic syndrome (1 paper, 2018). A cluster of metabolic risk factors for CARDIOVASCULAR DISEASES and TYPE 2 DIABETES MELLITUS. "All but four of the mapped genes (SIK3, SIDT2, UBASH3B, and CUX2) had been previously reported to be associated with metabolic syndrome, as indicated by a keyword search of “metabolic syndrome” in the GWAS catalog." (PMID 30382898, 2018). "SNPs on the UBASH3B and CUX2 genes could not be identified by single-SNP–multi-trait analysis, whereas the association of UBASH3B and CUX2 with metabolic syndrome-component traits was reported in the GWAS catalog." (PMID 30382898, 2018). "The relation of the individual SNPs, including those on SIK3, SIDT2, UBASH3B, and CUX2, to metabolic syndrome was further examined by single-SNP–multi-trait analysis, adjusted for age and sex." (PMID 30382898, 2018).
rheumatoid arthritis (1 paper, 2022). A chronic, systemic autoimmune disorder characterized by inflammation in the synovial membranes and articular surfaces. "We use molecular interaction and colocalisation analyses to identify multiple nuclear regulatory pathways linking meQTL loci to phenotypic variation, including UBASH3B (body mass index), NFKBIE (rheumatoid arthritis), MGA (blood pressure), and COMMD7 (white cell counts)." (PMID 34980917, 2022).
Thromboembolism (1 paper, 2020). The formation of a blood clot inside a blood vessel that subsequently travels through the blood stream from the site where it formed to another location in the body, generally leading to vascular occlusion at the distant site. "Another gene that regulates platelet and vascular homeostasis is UBASH3B (also known as TULA-2) and its low expression is associated with increased risk for thromboembolism in susceptible individuals." (PMID 33447134, 2020).
tumor (17 papers, 2016 to 2026). "In both subtypes, high UBASH3B expression is associated with poor patient outcomes, including increased tumor aggressiveness, metastasis, and resistance to treatment." (PMID 40885971, 2025). "In lung adenocarcinoma (LUAD), UBASH3B is implicated as a tumor suppressor, supported by evidence of its role in mitochondrial regulation." (PMID 40885971, 2025). "Recent studies have linked UBASH3B to tumor progression, immune evasion, and therapeutic resistance in several cancer types." (PMID 40885971, 2025). "These altogether suggested that UBASH3B and its associated genes were important for immune cells infiltration in tumor pathology." (PMID 32010618, 2019). "Together, these findings demonstrate UBASH3B as a tumor suppressor through its role in immune regulation, inhibition of oncogenic kinase activity, mitochondrial homeostasis, and maintenance of proper cell division." (PMID 40885971, 2025). "This insight underscores the importance of UBASH3B as a potential therapeutic target for enhancing NK cell-mediated anti-tumor immunity." (PMID 40486509, 2025). "UBASH3B plays an essential tumor-suppressive role through its regulation of tyrosine kinase signaling, immune signaling, and mitochondrial function." (PMID 40885971, 2025). "Given its widespread regulatory functions, research is exploring the role of UBASH3B in cancer cells, where it can influence oncogenic signaling pathways and tumor progression." (PMID 40885971, 2025). "Although UBASH3B has clear tumor-suppressive functions, numerous studies have also identified it as an oncogenic driver, particularly by disrupting ubiquitin-mediated degradation of oncogenic proteins and enhancing pro-tumorigenic signaling pathways." (PMID 40885971, 2025). "Mechanistically, UBASH3B promotes tumor progression by stabilizing the epidermal growth factor receptor (EGFR) levels, thereby enhancing downstream signaling pathways that promote cancer cell proliferation, survival, and therapeutic resistance." (PMID 40885971, 2025). "The distinct expression patterns observed in specific NK cell clusters and the correlations with inhibitory regulatory factors highlight UBASH3B’s potential role in modulating the immune response within the tumor microenvironment." (PMID 40486509, 2025). "The following sections will discuss the role of UBASH3B in contributing to tumor growth and metastasis." (PMID 40885971, 2025). "On the other hand, in TNBC, UBASH3B overexpression promoted cancer cell invasion and metastasis by downregulating the tumor-suppressive miR200a, a known suppressor of EMT." (PMID 40885971, 2025). "The literature and our study indicate that UBASH3B expression varies across different tumor types, potentially exerting opposite effects in different cancers." (PMID 39343960, 2024). "Since HSPA1B is negatively regulated by both UBASH3A and UBASH3B, its tumor suppressor activity is dependent upon balance between the level of these UBASH3 proteins, negatively and positively regulated by FLI1, respectively." (PMID 38461240, 2024). "In contrast to UBASH3B, knockdown of FLI1 in erythroleukemia cells upregulates UBASH3A expression, raising the possibility of a tumor suppressor function for this variant." (PMID 38461240, 2024). "Examination of various cohort databases indicated that low UBASH3B expression correlates with poor overall survival in LUAD patients, suggesting a potential tumor-suppressive role for UBASH3B in LUAD." (PMID 39343960, 2024). "Its paralog, UBASH3B is expressed in tumor-infiltrating CD8+ NK-like cells as well as CD8+ exhausted T cells." (PMID 37038005, 2023). "Our previous study indicated that lymphocyte cytosolic protein 2 (LCP2) protein tightly interacted with UBASH3B protein, which was identified as a novel prognostic biomarker and correlated with immune cell infiltration in the tumor microenvironment." (PMID 33911146, 2021).
tumor (continued). "The crosstalk between UBASH3B and tumor-infiltrating immune cells in PCa suggests a potential target of UBASH3B for future treatment of PCa." (PMID 32010618, 2019). "In order to know the relationship between UBASH3B expression and tumor-infiltrated immune cells, the tool of TIMER was used to analysis." (PMID 32010618, 2019). "The PPI network was constructed using STRING and the correlation between UBASH3B and tumor-infiltrating immune cells was analyzed by TIMER and CIBERSORT." (PMID 32010618, 2019). "UBASH3B exhibits dual expression patterns across multiple cancer types in the Pan-cancer analysis, functioning either as a tumor suppressor or oncogene, depending on the tumor type." (PMID 40885971, 2025). "Our results indicate that changes in UBASH3B expression may interfere with normal digestive system function and protein metabolism, impacting the immune state within the tumor microenvironment." (PMID 40486509, 2025). "Our research indicates that innate immune cell barrier genes, especially UBASH3B, may modulate the tumor microenvironment by influencing NK cell function and infiltration, thereby impacting the prognosis of PC patients." (PMID 40486509, 2025). "In addition, LCP2 protein tightly interacted with UBASH3B protein, which was identified as a novel prognostic biomarker and correlated with immune cell infiltration in the tumor microenvironment." (PMID 33911146, 2021). "Altogether, it was suggested that UBASH3B may participate in immune response in tumor microenvironment through affecting immune cells." (PMID 32010618, 2019). "However, the function of UBASH3B and the correlation of UBASH3B and tumor-infiltrating immune cells remain unclear." (PMID 32010618, 2019). "We found that overexpression of UBASH3B inhibited the tumor phenotype induced by MRPL12 WT overexpression but did not affect the tumor phenotype induced by MRPL12 Y60E overexpression." (PMID 39343960, 2024). "Thus, the combined oncogenic and tumor suppressor activities of UBASH3A and UBASH3B and their downstream effectors influence leukemogenesis." (PMID 38461240, 2024). "By constructing lncRNA-miRNA-mRNA and PPI networks, it was suggested that UBASH3B may interact with LCP2 and together participate in the immune response of tumor microenvironment." (PMID 32010618, 2019). "Aberrant expression of UBASH3B in triangle-negative breast cancer boosts tumor growth, invasion, and metastasis through EGFR regulation." (PMID 32010618, 2019).
cancer (9 papers, 2018 to 2025). A tumor composed of atypical neoplastic, often pleomorphic cells that invade other tissues. "UBASH3B has emerged as a promising oncogenic target due to its involvement in a multitude of cancer-associated pathways, including PI3K/Akt/mTOR, MAPK, and JAK-STAT signaling." (PMID 40885971, 2025). "In cancer studies, UBASH3B has been implicated in promoting tumorigenesis across various types of cancers, including prostate cancer, breast cancer, and leukemia." (PMID 40486509, 2025). "UBASH3B expression is implicated in various cancers through its ability to bind CBL and block its ubiquitination activity." (PMID 38461240, 2024). "Ubiquitin-associated and SH3 domain-containing B (UBASH3B) is involved in cancers pathogenesis and plays an important role in oncological biology by interacting with several molecules." (PMID 32010618, 2019). "Recent studies have linked UBASH3B dysregulation to cancer progression and proliferation." (PMID 40885971, 2025). "Moreover, a positive correlation between FLI1/UBASH3B was observed in several cancer types associated with worse prognosis." (PMID 38461240, 2024). "Together, the SH3 and UBA domains enable UBASH3B to orchestrate intricate protein interactions and regulatory mechanisms crucial for maintaining cellular homeostasis and controlling cancer development." (PMID 40885971, 2025). "Visualization using FeaturePlot and VlnPlot revealed that UBASH3B was significantly expressed in a subset of NK cells, T cells, myeloid cells, and cancer cells." (PMID 40486509, 2025). "Further studies are essential to validate the efficacy of cisplatin in inhibiting UBASH3B expression and to assess its potential as a combinatorial agent to restore chemotherapeutic drug sensitivity in cancer models." (PMID 40885971, 2025). "In this review, we aim to provide a comprehensive analysis of the different roles of UBASH3B in cancer initiation and progression, as well as its potential role in HNSCC, along with a focus on therapeutic responses." (PMID 40885971, 2025). "In this review paper, we have summarized current knowledge on UBASH3B, a multifunctional protein tyrosine phosphatase with a pivotal role in mammalian development and cellular signaling, with emerging significance in cancer and other diseases." (PMID 40885971, 2025). "Taken together, these findings highlight UBASH3B’s significance as a therapeutic target and emphasize the need for continued research to develop effective treatments targeting UBASH3B overactivity in cancer and other related conditions." (PMID 40885971, 2025). "Further scrutiny of a different LUAD TCGA dataset confirmed a significant downregulation of UBASH3B in LUAD tissues compared to para-carcinoma or matched adjacent tissues." (PMID 39343960, 2024). "Other significantly over-expressed genes in radioresistant PDOs – namely PLK2, UBASH3B, and NTN1 – have been associated with cancer progression." (PMID 35860583, 2022). "UBASH3B not only plays a critical role in the invasion and metastasis of cancer, but also affects the immune responses in cancer." (PMID 32010618, 2019). "Importantly, UBASH3B acts as a dual regulator of cancer progression and immune modulations, with its role varying depending on the cellular context." (PMID 40885971, 2025). "However, while these studies underscore the potential of PHPS1, further research is needed to optimize its specificity and evaluate its efficacy in preclinical models of UBASH3B-driven cancers." (PMID 40885971, 2025). "Additionally, the downregulation of UBASH3B can further potentiate the Spindle Assembly Checkpoint response inducing mitotic arrest and cell death in cancer cells expressing high levels of UBASH3B and Spindle Assembly Checkpoint proteins." (PMID 38339213, 2024).
cancer (continued). "To examine a broader role of these UBASH genes in cancer, we examined the correlation between FLI1 and UBASH3A or UBASH3B in the TCGA database by GEPIA2." (PMID 38461240, 2024). "Collectively, these pathways converge to promote critical hallmarks of cancer, including enhanced cell migration, invasion, EMT, and uncontrolled cell cycle progression, highlighting the hypothetical interplay between UBASH3B regulation and downstream oncogenic processes." (PMID 40885971, 2025). "In contrast, studies on UBASH3B’s role in cancer, especially PC, are relatively scarce, with no systematic reports available." (PMID 40486509, 2025). "miR-200a, a miRNA known to suppress invasion in various cancers, binds to the 3’ UTR of UBASH3B." (PMID 40885971, 2025). "UBASH3B contain an SH3 domains and could promote cancer progression by targeting CBL ubiquitin ligase for dephosphorylation and inactivation, which in turn leads to up-regulation and accumulation of activated EGFR." (PMID 29492198, 2018). "However, in the absence of UBASH3B, cancer cells expressing high levels of SAC proteins undergo mitotic arrest and cell death." (PMID 40885971, 2025). "Additionally, UBASH3B, CASP1, CARM1, CHAF1B and PCNT have been studied in other cancers." (PMID 37894336, 2023).
UBASH3B also shares sentences with these, for which no sentence is quoted: infection (4 papers); benign prostatic hyperplasia (2); colitis (2); Arthritis (1); cardiovascular diseases (1); disseminated candidiasis (1); experimental autoimmune encephalomyelitis (1); fatty liver (1); head and neck cancer (1); inflammatory bowel disease (1); Lung squamous cell carcinoma (1); myocardial infarction (1); neurological diseases (1); Obesity (1); pancreatic adenocarcinoma (1); pancreatic cancer (1); Parkinson’s (1); Stroke (1); systemic lupus erythematosus (1); thrombosis (1).